TRIM44 (tripartite motif containing 44)
Diseases named in the same sentence as TRIM44 in open-access papers (continued):
Sharing a sentence is not in itself a finding about the gene and the disease.
papillary thyroid cancer (2 papers, 2022 to 2024). "Zhou Z and others found that TRIM44 is highly expressed in human papillary thyroid carcinoma and increases the proliferation and invasion of papillary thyroid cancer cells by activating the Wnt/β-catenin signaling pathway." (PMID 36249749, 2022). "In human papillary thyroid cancer (PTC) cells, TRIM44 knockdown inhibited the proliferation, migration and invasion of PTC cells by inactivating the Wnt/β-catenin signaling pathway; and LiCl, an activator of the Wnt/β-catenin pathway, rescued the anticancer effect of TRIM44 knockdown in PTC cells." (PMID 36249749, 2022).
aniridia (1 paper, 2024). Aniridia is a congenital ocular malformation characterized by the complete or partial absence of the iris. "Isolated aniridia can be caused by point mutations in the PAX6 gene (aniridia type 1), ELP4 gene (chromosome 11p13) (aniridia type 2), and TRIM44 gene (chromosome 11p13) (aniridia type 3)." (PMID 39600756, 2024).
bladder cancer (1 paper, 2025). "This suggests that TRIM44 overexpression caused by ELDR probably acts in bladder cancer by making this essential cancer-causing pathway work too hard." (PMID 41357604, 2025). "The precise molecular effects triggered by the upregulation of TRIM44 in bladder cancer require further investigation." (PMID 41357604, 2025). "Collectively, these findings delineate the ELDR/miR-1343-3p/TRIM44 axis as a functionally independent pathway that expands the known regulatory network of lncRNAs in bladder cancer pathogenesis." (PMID 41357604, 2025). "Finally, the role of the ELDR-miR-1343-3p-TRIM44 axis in bladder cancer cell behavior was demonstrated." (PMID 41357604, 2025). "Finally, confirmatory validation of the proposed downstream pathways—particularly the direct activation mechanism of the PI3K/AKT pathway and the role of TRIM44 in inducing epithelial-mesenchymal transition (EMT) in bladder cancer—has become the core focus of our current research." (PMID 41357604, 2025).
cardiac hypertrophy (1 paper, 2023). "Furthermore, Trim44 deficiency in the myocardium resulted in inhibition of activation of pathways involved in myocardial hypertrophy in response to pathological stress." (PMID 35855640, 2023). "Furthermore, signal transduction validation associated with growth and hypertrophy development in vivo and in vitro demonstrated that Trim44 deficiency inhibited the activation of signaling pathways involved in myocardial hypertrophy, especially response to pathological stress." (PMID 35855640, 2023). "Furthermore, signal transduction validation in vivo and in vitro demonstrated that Trim44 deficiency in the myocardium inhibited the activation of cascade pathways involved in cardiac hypertrophy, AKT/mTOR/GSK3β/P70S6K, especially response to pathological stress." (PMID 35855640, 2023). "The abnormally increased expression of Trim44 under pathological cardiac hypertrophy/HF states prompted us to further investigate the biological function of Trim44 in heart, especially in response to stress." (PMID 35855640, 2023). "As expected, the inhibitory effects of Trim44 KO on pathological cardiac hypertrophy induced by ISO treatment were exerted by suppressing the AKT/mTOR/GSK3β/P70S6K signaling pathway." (PMID 35855640, 2023). "Moreover, we found that Trim44 expression increased under pathological stimulation of cardiac hypertrophy and was mainly distributed in the cytoplasm." (PMID 35855640, 2023). "However, the inhibitory effects of Trim44 KO on pathological cardiac hypertrophy induced by ISO treatment were exerted by suppressing the AKT/mTOR/GSK3β/P70S6K signaling pathway." (PMID 35855640, 2023). "Furthermore, the expression of Trim44 was also increased obviously in ISO-induced or angiotensin (ANG II)-induced cardiac hypertrophy/HF rat models (n=4 rats per group, P<0.001, ISO- or ANG II-treated group versus the saline group)." (PMID 35855640, 2023). "Therefore, we evaluated the expression of TRIM44 in samples of patients with pathological cardiac hypertrophy." (PMID 35855640, 2023). "Therefore, we detected the activation of those signaling pathways in heart tissues from Trim44 KO rats, especially under the pathological stimulus of cardiac hypertrophy/HF." (PMID 35855640, 2023). "Trim44 could be a novel therapeutic target for prevention of cardiac hypertrophy and HF." (PMID 35855640, 2023). "However, when given a pathological stimulus, the inhibition of myocardial hypertrophy signals with Trim44 KO is clearly apparent, suggesting that Trim44 may mainly be involved in the regulation of pathological myocardial hypertrophy." (PMID 35855640, 2023). "However, the effects of Trim44 KO under pathological stress of cardiac hypertrophy/HF were still unknown." (PMID 35855640, 2023). "Trim44 could be a novel therapeutic target for prevention of cardiac hypertrophy." (PMID 35855640, 2023). "Therefore, we then subjected both the Trim44 KO rats and control rats to ISO treatment to mimic pathological cardiac hypertrophy/HF stimulation." (PMID 35855640, 2023). "Therefore, it is speculated that Trim44 may regulate the ubiquitination level of TLR4 in myocardium, affecting the activation state of the AKT/mTOR signaling pathway and thus participating in the regulation of cardiac hypertrophy." (PMID 35855640, 2023). "We further analyzed the expression of Trim44 in rat myocardial tissues of cardiac hypertrophy induced by ISO through immunohistochemical observation, and we also verified the lack of Trim44 staining in myocardial tissues from Trim44 KO rats." (PMID 35855640, 2023).
cardiac interstitial fibrosis (1 paper, 2025). "We further revealed that Kdm4a induces the premature senescence of fibroblasts by depressing cell autophagy through the H3K9me3 modification of Trim44, resulting in cardiac interstitial fibrosis." (PMID 40231733, 2025). "It verified that Kdm4a downregulation promotes autophagy in premature senescent fibroblasts by increasing the H3K9m3 modification of the Trim44 promoter, significantly suppressing premature senescence in fibroblasts, and ultimately reducing cardiac interstitial fibrosis." (PMID 40231733, 2025). "In conclusion, premature senescent fibroblasts play a pivotal role in promoting cardiac interstitial fibrosis in the advanced stage after MI without affecting replacement fibrosis, which can be inhibited by Kdm4a deletion through Trim44‐mediated autophagy of premature senescent fibroblasts." (PMID 40231733, 2025).
cervical cancer (1 paper, 2019). A primary or metastatic malignant neoplasm involving the cervix. "As for TRIM44, our study is the first report to assess the TRIM44 expression as well as its association with clinical pathological features in cervical cancer." (PMID 30792262, 2019). "The present study suggests that enhanced TRIM44 levels may be closely associated with the pathogenesis and poor prognosis of cervical cancer." (PMID 30792262, 2019). "We found that TRIM44 is overexpressed in cervical cancer and is closely related to tumor progression and unfavorable outcome." (PMID 30792262, 2019). "Taken together, those studies make a positive contribution to investigate the molecular mechanism by which TRIM44 participates in the migration and invasion in cervical cancer." (PMID 30792262, 2019). "Of the 122 cervical cancer cases, 41 (33.6%) and 81 (66.4%) showed low and high TRIM44 expression, respectively." (PMID 30792262, 2019). "In the present study, we investigated the expression of TRIM44 in cervical cancer and assessed the role of TRIM44 in the progression of cervical cancer." (PMID 30792262, 2019). "TRIM44 expression was found to be significantly up-regulated in cervical cancer specimens compared with adjacent normal tissues (P<0.001)." (PMID 30792262, 2019). "The results of the present study suggest that TRIM44 expression was significantly up-regulated in cervical cancer specimens compared with adjacent normal tissues and was significantly associated with poor prognosis." (PMID 30792262, 2019). "The purpose of this study was to investigate the clinical significance of TRIM44 expression and the prognosis in patients with cervical cancer (CC)." (PMID 30792262, 2019). "RT-PCR result showed that the mean expression level of TRIM44 mRNA was significantly higher in cervical cancer tissues than in normal cervical tissues (P<0.05)." (PMID 30792262, 2019). "The immunohistochemistry analysis showed that TRIM44 expression was localized in the cytoplasm of cervical cancer cells." (PMID 30792262, 2019). "Significant statistical differences in TRIM44 expression were observed between cervical cancer tissues and their adjacent normal tissues." (PMID 30792262, 2019). "The mRNA and protein level of TRIM44 was significantly higher in cervical cancer tissues compared with adjacent normal tissues (P<0.001)." (PMID 30792262, 2019). "In general, higher expression of TRIM44 indicated a clinically more malignant cervical cancer." (PMID 30792262, 2019). "Our study demonstrated that TRIM44 expression contributes to the progression of cervical cancer, and could be used as a marker of clinical diagnosis and prognosis of patients with cervical cancer." (PMID 30792262, 2019). "Therefore, TRIM44 could be an oncogene for cervical cancer development and patient prognosis." (PMID 30792262, 2019). "However, the potential involvement of TRIM44 in cervical cancer and the related mechanisms have not been fully explored." (PMID 30792262, 2019).
clear cell renal cell carcinoma (1 paper, 2025). "Tripartite motif-containing 44 (TRIM44), a member of the TRIM protein family, has emerged as a regulator in multiple cancer types, yet its functional role and molecular mechanisms in clear cell renal cell carcinoma (ccRCC) remain poorly characterized." (PMID 40967439, 2025).
esophageal adenocarcinoma (1 paper, 2014). A malignant tumor with glandular differentiation arising predominantly from Barrett mucosa in the lower third of the esophagus. "A panel of three proteins (EGFR, TRIM44, and SIRT2) had been shown to determine prognosis for esophageal adenocarcinoma (EAC), and a combination of this panel and clinicopathologic features could stratify patients into subgroups with different prognosis." (PMID 25337715, 2014).
growth disorders (1 paper, 2020). "Tripartite motif-containing 44 (TRIM44) localized in the cytoplasmic compartment of cells was reported to contribute to diverse pathological conditions, such as tumors, growth disorders, and neurodegeneration." (PMID 32503466, 2020).
metastatic tumors (1 paper, 2022). "Overall, the three most highly expressed genes are TRIM28, TRIM44, and TRIM8 in the primary and metastatic tumors and normal tissues." (PMID 35928444, 2022).
seminoma (1 paper, 2021). A radiosensitive malignant germ cell tumor found in the testis (especially undescended), and extragonadal sites (anterior mediastinum and pineal gland). "Therefore, both the epigenetic status of the FLNA promoter and expression of the TRIM44-SQSTM1/p62-filamin A protein loop represent potential targets for therapy-resistant CS I seminomas." (PMID 34771736, 2021).
squamous cell carcinoma (1 paper, 2016). A carcinoma arising from squamous epithelial cells. "High expression of TRIM44 was less frequent in squamous cell carcinoma (SCC) cases than in adenocarcinoma (ADC) cases (52.3% vs. 72.2%, respectively; P < 0.001)." (PMID 27058415, 2016).
cancer (32 papers, 2016 to 2025). A tumor composed of atypical neoplastic, often pleomorphic cells that invade other tissues. "To elucidate the mechanism by which TRIM44 orchestrates BRCA1-mediated HR repair and cisplatin resistance, we reviewed all publications linked to TRIM44 in cancer." (PMID 35541909, 2022). "Overexpression of TRIM44 has been shown to induce a similar change in hallmark characteristics of EMT in other cancers, such as ICC and HEC." (PMID 32503466, 2020). "Despite this evidence, only a handful of publications link TRIM44 function with cancers and the mechanisms underlying this association are even less clear." (PMID 30922374, 2019). "TRIM44 IR is also positively associated with nuclear grade (NG), which is assumed to be a poor prognostic factor that represents proliferative activity of cancer cells and nuclear atypia." (PMID 28885545, 2017). "Accumulating evidence indicates that the crucial roles of TRIM44 in the development of various types of malignant tumors." (PMID 41357604, 2025). "While the ceRNA paradigm and the oncogenic role of TRIM44 have been documented in various cancer types, the upstream regulators that dictate TRIM44 expression in BCa remain poorly characterized." (PMID 41357604, 2025). "To date, there is convincing evidence that the function of TRIM44 is related to immune regulation, viral infection, and cancers." (PMID 39757165, 2025). "Previous reports identified NFκβ signaling pathway as a target pathway of TRIM44 in cancers of the larynx, lung, liver, breast, colorectal, and ovary." (PMID 40723250, 2025). "The analysis results revealed that overexpression of TRIM44 protein was significantly associated with shorter OS and poorer disease‐free survival (DFS) in malignant tumor patients." (PMID 39667820, 2024). "Specifically, TRIM14, TRIM25, TRIM32, TRIM44, TRIM59, and TRIM29 exhibit abnormal expression in different cancer types and have been linked to patient prognosis." (PMID 39273003, 2024). "Tripartite motif containing 44 (TRIM44) regulates the DNA damage response in cancer cells with intact autophagy by preventing degradation of FLNA, increasing DNA damage repair." (PMID 39195282, 2024). "Consistently, based on The Cancer Genome Atlas (TCGA) database, Gene Ontology (GO) enrichment analysis indicated that TRIM44 functions in “DNA repair”." (PMID 35541909, 2022). "Earlier studies found that TRIM44 over-expression was present in many cancers, which stimulated development, proliferation, and progression of the cell cycle." (PMID 35071748, 2022). "Increasing evidence indicates that TRIM44 plays pivotal roles in tumor progression, as it can potentiate the proliferation, migration and invasion of cancer cells and can induce drug resistance and radioresistance 9-11, 15-27." (PMID 35541909, 2022). "Tripartite motif containing 44 (TRIM44), an important member of the TRIM family, contributes to a variety of pathological states and is closely associated with malignant tumor etiology and progression." (PMID 34677810, 2021). "The GEPIA analysis results showed that TRIM44 was frequently overexpressed in multiple malignant tumors, and cancer patients with increased tissue TRIM44 expression had unfavorable prognosis." (PMID 32503466, 2020). "Some studies have suggested that TRIM44 plays a cancer-promoting role in oncogenesis and tumor progression, and increased TRIM44 expression was detected in cancer tissues and it was associated with poor prognosis and advanced clinicopathological parameters." (PMID 32503466, 2020). "TRIM44 overexpression leads to high mTOR activity, which is consistent with observations of reduced mTOR signaling in cancer cell lines after siRNA knockdown of TRIM44." (PMID 32503466, 2020). "TRIM44 protein and mRNA have been reported to be significantly upregulated in cancer tissues compared to para-cancerous or normal samples." (PMID 32503466, 2020).
cancer (continued). "It has been demonstrated that Trim44 is involved in the development and progression of several malignant tumors." (PMID 30792262, 2019). "Tripartite motif containing 44 (TRIM44) has been reported to be up-regulated in multiple aggressive malignant tumors." (PMID 30792262, 2019). "A search of the integrated cancer microarray database (Oncomine) revealed that TRIM44 mRNA expression is significantly upregulated in MM compared to normal or MGUS (a precursor stage of MM) in two different datasets." (PMID 30089913, 2019). "Firstly, we analyzed the level of TRIM44 in three human digestive cancers from the Oncomine database, which contains cDNA microarray data for cancer and matched normal tissues." (PMID 29446253, 2018). "Firstly, TRIM44 expression was analyzed in several kinds of cancers by referring to public Oncomine database, and the expressions of TRIM44 mRNA and protein were tested in ICC and corresponding paratumorous tissues." (PMID 29446253, 2018). "To date, several studies have reported that TRIM44 contributes to diverse pathological conditions such as cancer, developmental disorders, neurodegenerative diseases, and viral infections." (PMID 27058415, 2016). "The role of TRIM44 mRNA, protein, and activity in the development and progression of several malignant tumors has been examined." (PMID 27058415, 2016). "TRIM44 overexpression was associated with alpha feto protein levels, clinical stage, nonseminomatous germ cell tumor, and cancer-specific survival." (PMID 40723250, 2025). "TRIM44 is also among the downstream targets of circRNA in regulating glycolysis in cancer." (PMID 40723250, 2025). "TRIM44 may serve as a valuable prognostic biomarker and potential therapeutic target for malignant tumor patients." (PMID 39667820, 2024). "TRIM44 may act as a cancer-promoting gene regulating deubiquitination and stabilization of oncogenes." (PMID 32503466, 2020). "Furthermore, cancer patients with unfavorable clinicopathological parameters more frequently showed overexpression of TRIM44 protein." (PMID 32503466, 2020). "TRIM32, TRIM28, and TRIM44 promote cancer progression by activating β-catenin signaling." (PMID 32802046, 2020). "The interactions of the Wnt/β-catenin pathway and other members of the TRIM protein family, such as TRIM29, TRIM28, TRIM32, TRIM33, and TRIM44, may play important roles in the development of human cancers." (PMID 32802046, 2020). "Importantly, recent studies have revealed that high levels of TRIM44 induce the epithelial-to-mesenchymal transition (EMT) in cancer cells and that TRIM44 promotes tumor initiation and progression by activating the PI3K/AKT/mTOR pathway." (PMID 32503466, 2020). "For example, TRIM44 is upregulated in head and neck squamous cell carcinoma, lung cancers, prostate cancers and hepatocellular carcinoma with functions varies from promoting migration and invasion to enhancing drug resistance in cancer cells." (PMID 30089913, 2019). "Recent studies have demonstrated a multifaceted role of TRIM44 in cancer progression." (PMID 30792262, 2019). "These previous studies have revealed that TRIM44 is involved in the migration and invasion of malignant tumors, which indicated that TRIM44 may be useful as a clinically relevant prognostic biomarker and a new therapeutic target in the future." (PMID 30792262, 2019). "Several studies report that TRIM44 plays a crucial role in the progression of human cancers." (PMID 30922374, 2019). "So far, the mechanism underlying the TRIM44-dependent activation of NF-κB signaling has not been well clarified in cancers." (PMID 28885545, 2017). "Therefore, the mechanism by which TRIM44 contributes to cancer progression is both important and interesting." (PMID 27058415, 2016). "In addition, we showed that TRIM44 overexpression leads to high mTOR activity, a finding supported by the reduced mTOR signaling in cancer cell lines after siRNA knockdown of TRIM44, and colocalization of TRIM44 with p-mTOR in patient samples." (PMID 27058415, 2016).